TACC3 (transforming acidic coiled-coil containing protein 3)
Diseases named in the same sentence as TACC3 in open-access papers (continued):
Sharing a sentence is not in itself a finding about the gene and the disease.
glioma (49 papers, 2010 to 2025). A benign or malignant brain and spinal cord tumor that arises from glial cells (astrocytes, oligodendrocytes, ependymal cells). "Among gliomas with FGFR3::TACC3 fusion, age, TERT promoter mutation, pathological features, DNA-methylation profiling and fusion subtype are of interest to determine patients’ risk." (PMID 36647073, 2023). "In the CGGA miRNA dataset, these TACC3 negatively associated miRNAs were significantly downregulated in high grade glioma (except for miR-330-3p, p = 0.4164)." (PMID 28273854, 2017). "In the present study, we analyzed transcriptome-clinical data from the CGGA dataset and revealed that TACC3 was upregulated along with glioma progression and inversely associated with patients’ prognosis." (PMID 28273854, 2017). "In present study, we analyzed CGGA sequencing and array data to explore the diagnostic, prognostic and therapeutic implications of TACC3 and delineate the TACC3-miRNA-mRNA network in glioma patients." (PMID 28273854, 2017). "The molecular characterization of fusion-positive glioma revealed that FGFR3::TACC3 is mutually exclusive with IDH and H3 mutation but it is often associated with TERT promoter mutation and + 7/−10 chromosome copy-number changes and amplification of CDK4 and /or MDM2." (PMID 36647073, 2023). "The F3-T3 fusion gene, formed from the combination of the FGFR3 and TACC3 genes, is detected in approximately 3% of gliomas and other malignant tumors, marking it as a notable oncogenic fusion gene." (PMID 40265014, 2025). "Taken together, these findings suggest a wide spectrum of radiological appearances in FGFR3::TACC3 fusion-positive gliomas." (PMID 40417325, 2025). "Assessment of FGFR3 immunohistochemical expression represents a useful screening tool for the identification of F3T3 gliomas with FGFR3::TACC3 fusion." (PMID 38730596, 2024). "Chromosomal translocations that fuse the tyrosine kinase domains of FGFR1 or FGFR3 and TACC1 or TACC3 have been identified in 2% to 4% of gliomas." (PMID 39087020, 2024). "Diffuse gliomas with FGFR3::TACC3 fusion display unique histopathological and molecular features, including an oligodendroglioma-like appearance, calcifications, and CD34 extravascular immunoreactivity." (PMID 38730596, 2024). "In a study, next-generation sequencing demonstrated higher sensitivity in identifying FGFR3::TACC3 fusions in gliomas than RT-PCR performed on frozen tissue." (PMID 38730596, 2024). "In contrast, gliomas with FGFR3(Ex17)::TACC3(Ex10) fusion had a significantly better OS (p = 0.032) but PFS was not significantly different (p = 0.328)." (PMID 36647073, 2023). "The frequency of FGFR3::TACC3 fusion in gliomas with pathological features of low grade is more difficult to appreciate but does not exceed 4% in some studies." (PMID 36647073, 2023). "Four genes showed a higher fusion rate in OAs included NAB2 (0.4% vs. 4.2%) and STAT6 (0.4% vs. 2.9%) in soft tissue sarcoma and FGFR3 (0.4% vs. 3.1%) and TACC3 (0 vs. 3.0%) in glioma." (PMID 36433963, 2022). "Although the dysfunction of TACC3 is thought to have oncogenic implications in a spectrum of cancers, little is known about its expression pattern and potent mechanism in glioma." (PMID 28273854, 2017). "Collectively, our observations identify TACC3 as an oncogene of tumor malignancy, as well as a prognostic and motoring biomarker for glioma patients." (PMID 28273854, 2017). "To investigate the predictive implication of TACC3 in glioma prognosis, we analyzed TACC3 expression and the OS in the CGGA database." (PMID 28273854, 2017). "Multivariable Cox analysis confirmed that TACC3 served as an independent prognostic indicator for glioma patients’ treatment." (PMID 28273854, 2017).
glioma (continued). "Our observations explicitly showed that along with TACC3 upregulation, patients were prone to be with the G3 subtype, classical/mesenchymal subtype and high grade glioma." (PMID 28273854, 2017). "Here, we propose an oncogenic implication of transforming acidic coiled-coil-containing protein 3 (TACC3) in gliomas." (PMID 28273854, 2017). "These imaging findings may also reflect microcalcifications frequently reported in the histopathology of FGFR3::TACC3 fusion-positive gliomas." (PMID 40417325, 2025). "Diffuse gliomas with fibroblast growth factor receptor 3 (FGFR3) and transforming acidic coiled-coil containing protein 3 (TACC3) gene fusion represent a distinct molecular subtype of isocitrate dehydrogenase (IDH)-wildtype gliomas characterized by unique histopathological features." (PMID 40417325, 2025). "Previous radiological imaging studies of FGFR3::TACC3 fusion-positive gliomas have reported a tendency for these tumors to localize to the cortex or subcortical white matter, particularly in the frontal or temporal lobes, with relatively well-circumscribed margins in a subset of cases based on MRI." (PMID 40417325, 2025). "Diffuse gliomas with FGFR3::TACC3 fusion (F3T3 gliomas) may potentially be treated with FGFR inhibitors." (PMID 38730596, 2024). "However, trials testing the efficacy of FGFR inhibitors in patients with F3T3 gliomas have demonstrated only moderate efficacy in comparison to the remarkable results obtained in other cancers harboring the FGFR3::TACC3 fusion." (PMID 38730596, 2024). "Importantly, fewer than 15 FGFR3::TACC3 pediatric gliomas, presenting initially with LGG histological features, have been reported to date, including one case of PLNTY with secondary malignant transformation." (PMID 36647073, 2023). "In addition to the epigenetic heterogeneity, we also observed that the clinical behavior of glioma with FGFR3::TACC3 fusion was also heterogeneous with some patients that had a stable disease in contrast to others." (PMID 36647073, 2023). "Interestingly, the FGFR3::TACC3 fusion is considered an FGFRi predictive biomarker in gliomas (NCT02824133, NCT04424966) and cholangiocarcinoma (NCT03773302)." (PMID 36142417, 2022). "FGFR3 fusion with TACC3 was the classic fusion type that happened in glioma." (PMID 34160364, 2021). "In conclusion, our present work demonstrated that TACC3 is an oncogene for glioma progression." (PMID 28273854, 2017). "The high expression of TACC3 in malignant gliomas suggested that TACC3 may serve as an oncogene during glioma progression." (PMID 28273854, 2017). "Moreover, cell cycle and DNA repair-associated GO biological processes were also significant for glioma patients with high TACC3 expression." (PMID 28273854, 2017). "We found significant overexpression of TACC3 in Grade IV gliomas." (PMID 21113414, 2010). "Additionally, TACC3-related miRNA-mRNA interactions were identified after in silico prediction and large-scale verification, providing an alternative approach for miRNA-based glioma precision medicine." (PMID 28273854, 2017). "Therefore, we speculated that TACC3 could benefit tumor cells treated with therapeutic approaches, which will decrease the overall survival of glioma patients." (PMID 28273854, 2017). "In the present study, we identified ten TACC3 negative-associated miRNAs in glioma patients." (PMID 28273854, 2017). "In gliomas, FGFR overexpression or gene fusion events, notably the FGFR3-tyransforming acidic crimp 3 (TACC3) fusion, can aberrantly activate these downstream pathways, promoting tumor cells proliferation, migration, and invasion." (PMID 41567627, 2025). "In this review, we summarize the histopathological and molecular features of F3T3 gliomas, the current challenges in the diagnosis and classification of these tumors, and methods for detecting FGFR3::TACC3 fusion in tumor tissue." (PMID 38730596, 2024).
glioma (continued). "In our series of diffuse gliomas with FGFR3::TACC3 fusion, PFS (p = 0.029) and OS (p = 0.001) were significantly worse in gliomas demonstrating FGFR3(Ex17)::TACC3(Ex11) fusion." (PMID 36647073, 2023). "The FGFR3 fusion types observed in glioma (GBM and LGG) in our analysis included FGFR3-TACC3, TACC3-FGFR3, FGFR3-AMBRA1, FGFR3-ELAVL3, FGFR3-FBXO28, and TACC3 was observed to be the most common partner gene of FGFR3 fusion." (PMID 34160364, 2021). "Therefore, we speculated that TACC3 could stratify glioma patients according to its expression." (PMID 28273854, 2017). "Patients with high TACC3 expression showed CD133+ stem cell properties, glioma plasticity and shorter overall survival time under chemo-/radio-therapy." (PMID 28273854, 2017). "FGFR3::TACC3 fusion has been identified in approximately 4% of diffuse gliomas, IDH-wildtype, highlighting the distinct molecular and pathological characteristics that distinguish it from other glioma subtypes [2,]." (PMID 40417325, 2025). "It should be noted that F3T3 gliomas lacking pTERT mutations, those having other FGFR3::TACC3 fusions besides FGFR3 (ex17)::TACC3 (ex11), or those resected from patients younger than 40 years exhibit a significantly better prognosis." (PMID 38730596, 2024). "Notably, high-grade F3T3 gliomas had a significantly lower mitotic rate and a higher vascular density than GBM IDH-wildtype devoid of the FGFR3::TACC3 fusion." (PMID 38730596, 2024). "Diffuse gliomas with FGFR3::TACC3 fusion are not recognized as a distinct tumor type in the 2021 WHO classification of CNS tumors, which is in keeping with their clinical and epigenetic heterogeneity." (PMID 36647073, 2023). "This demonstrated that DNMT1, IDH3A, TACC3, and TKT could be incorporated as prognostic markers for glioma." (PMID 37875819, 2023). "By comprehensively analyzing the Chinese glioma genome atlas (CGGA) and publicly available data, we demonstrated that TACC3 were overexpressed along with glioma grade and served as an independent negative prognostic biomarker for glioma patients." (PMID 28273854, 2017). "However, the radiological imaging characteristics of FGFR3::TACC3 fusion-positive gliomas have not yet been fully elucidated, posing challenges in distinguishing them from other diffuse gliomas." (PMID 40417325, 2025). "Furthermore, one case reported as PLNTY and harboring FGFR3::TACC3 fusion displayed a clinical course atypical for PLNTY and underwent malignant transformation, reinforcing the notion that PLNTY and histologically low-grade F3T3 gliomas are distinct tumor types." (PMID 38730596, 2024). "However, the expression pattern and latent functions of TACC3 in glioma is not well investigated." (PMID 28273854, 2017). "A comparison between 34 high-grade F3T3 gliomas and 100 GBM IDH-wildtype cases lacking FGF3::TACC3 fusion revealed that the former were more likely to be assigned the mesenchymal or RTK II subclass than the latter." (PMID 38730596, 2024).
bladder cancer (45 papers, 2013 to 2025). "A known GWAS-identified bladder cancer susceptibility SNP, rs798766 of TACC3 (near FGFR3), was among SNPs associated with FAM53A expression in whole blood." (PMID 39789109, 2025). "To identify upstream regulators of TACC3, we first analyzed genes positively associated with TACC3 mRNA levels using mRNA expression profiles from 34 bladder cancer cell lines in the DepMap (23Q4) database." (PMID 40246827, 2025). "The upregulation of TACC3 was positively associated with tumor invasiveness, grade, T stage, and progression in patients with bladder cancer." (PMID 29358577, 2018). "Here, we investigate the association between FT3 and mitotic defects observed in bladder cancer cells and describe a TACC3-specific role for FT3 in this process." (PMID 28855393, 2017). "In summary, this meta-analysis suggests that the TACC3 rs798766 polymorphism is significantly associated with increased risk of urinary bladder cancer." (PMID 28655970, 2017). "A possible association between the TACC3 rs798766 polymorphism and urinary bladder cancer risk has been indicated in published literature." (PMID 28655970, 2017). "It is upregulated by multiple mechanisms in bladder cancer cells: 1) somatic mutation, 2) over-expression of the wild-type protein, or 3) gene fusion with transforming acid coiled coil (TACC3) or BAI-1 associated protein 2-like 1 (BAI1AP2L1) partners." (PMID 25909217, 2015). "Previously, in one of the publications based on our GWAS for bladder cancer risk, we described association of the rs798766[T] allele (TACC3/FGFR3 locus) with an increased risk of disease recurrence among low-stage low-grade NMIBC cases." (PMID 24586564, 2014). "In addition, several Genome-wide association study (GWAS) have identified TACC3 as a candidate bladder cancer susceptibility gene." (PMID 29358577, 2018). "TACC3 may therefore serve as a potential prognostic and diagnostic indicator and as a therapeutic target in bladder cancer." (PMID 29358577, 2018). "Interestingly, several bladder cancer risk variants including MYC and FGFR3/TACC3 show stronger association with low risk tumors, confirming the heterogeneous nature of bladder cancer." (PMID 23752272, 2013). "In addition, high TACC3 expression was significantly associated with gender (p = 0.013), invasiveness (p < 0.001), tumor grade (p < 0.001), tumor progression (p = 0.001), and T status (p < 0.001) in bladder cancer patients." (PMID 29358577, 2018). "Here, we demonstrate that TACC3 promotes glycolysis in bladder cancer (BC) by interacting with c-Myc, enhancing its acetylation at lysine 323 (K323) and thereby stabilizing the c-Myc protein." (PMID 40246827, 2025). "In bladder cancer (BC), chromosomal translocations can fuse TACC3 to FGFR3, resulting in constitutive activation of FGFR3 kinase and driving cellular transformation." (PMID 40246827, 2025). "In this study, we demonstrate that E2F3 directly activates the transcription of TACC3 in bladder cancer." (PMID 40246827, 2025). "Our work demonstrates that TACC3 overexpression promotes aerobic glycolysis in bladder cancer (BC) cells, accompanied by the upregulation of glycolytic genes." (PMID 40246827, 2025). "To investigate the molecular mechanisms by which TACC3 promotes malignant phenotypes in bladder cancer, we performed RNA-seq analysis of 5637 cells with stable TACC3 knockdown compared to control cells." (PMID 40246827, 2025). "To evaluate the effect of TACC3 on bladder cancer (BC) growth in vivo, we established a xenograft model by subcutaneously injecting TACC3-knockdown 5637 cells and control cells into mice." (PMID 40246827, 2025). "Studies have shown that TACC3 is highly expressed in lung cancer, bladder cancer, multiple myeloma, osteosarcoma, prostate cancer, glioblastoma, ovarian cancer, and colorectal cancer." (PMID 34149795, 2021).
bladder cancer (continued). "Recurrent intrachromosomal fusions betweenFGFR1 and TACC1, and FGFR3 and TACC3 occur in approximately 3% of glioblastomamultiforme and 4% of bladder cancer, respectively." (PMID 32315352, 2020). "Herein, we demonstrate that TACC3 is upregulated gradually as bladder cancer progresses and that normal tissues exhibited the lowest expression of TACC3, followed by NMIBCs and MIBCs." (PMID 29358577, 2018). "Since cisplatin-based chemotherapy is a classic treatment for bladder cancer, we wanted to elucidate the relationship of TACC3 expression and cisplatin sensitivity." (PMID 29358577, 2018). "Since our results suggested that TACC3 has a role in the transition from G1 to S phase in bladder cancer cells, we performed a western blot to analyze the expression of key cell-cycle regulatory proteins after modulation of TACC3 expression." (PMID 29358577, 2018). "In the current study, we found that TACC3 expression levels are significantly elevated in bladder cancer, and more importantly that they are positively correlated with tumor progression and poor prognosis." (PMID 29358577, 2018). "In the present study, we reported that TACC3 was markedly elevated in bladder cancer, especially in muscle-invasive bladder cancers (MIBCs)." (PMID 29358577, 2018). "We initially examined TACC3 expression in bladder cancer tissues and in normal bladder epithelium by Quantitative Polymerase Chain Reaction (QPCR)." (PMID 29358577, 2018). "Collectively, these results provided evidence that TACC3 contributes to G1/S phase progression in the cell cycle in bladder cancer cells." (PMID 29358577, 2018). "Functional studies have found that TACC3 is a prerequisite for the development of malignant characteristics of bladder cancer cells, including cell proliferation and invasion." (PMID 29358577, 2018). "To investigate the biologic activities of TACC3 in bladder cancer, we first examined the effect of siRNA-induced reduction of TACC3 by western blot and Real-time Quantitative Polymerase Chain Reaction qRT-PCR." (PMID 29358577, 2018). "Knockdown of the fusion gene or low-level overexpression of TACC3 partially rescues the chromosome segregation defects in FT3-positive bladder cancer cells." (PMID 28855393, 2017). "Here we show that FT3-positive bladder cancer cells have lower levels of endogenous TACC3 on the mitotic spindle, and that this is sufficient to cause mitotic defects." (PMID 28855393, 2017). "In this paper, we have shown a TACC3-specific role of FT3 in inducing mitotic defects in bladder cancer cells." (PMID 28855393, 2017). "Together, these findings demonstrate that TACC3 enhances glycolysis in bladder cancer." (PMID 40246827, 2025). "Future studies should investigate a potential cross-regulatory loop between E2F family members and TACC3, which could create a feedforward or feedback mechanism that amplifies oncogenic signaling in bladder cancer." (PMID 40246827, 2025). "Taken together, these observations suggested that altered TACC3 expression might be instrumental in the initiation or progression of bladder cancers." (PMID 29358577, 2018). "According to these findings, when exposed to a higher dose of cisplatin (10 μg/ml), bladder cancer cell lines with high TACC3 or E2F1 expression were both characterized by a strong transactivation response by Bik and Bim, which paralleled a severe downregulation of the Bcl-2 gene." (PMID 29358577, 2018). "Furthermore, a Kaplan–Meier survival analysis showed that patients with bladder cancer whose tumors had high TACC3 expression experienced a dismal prognosis compared with patients whose tumors had low TACC3 expression." (PMID 29358577, 2018). "In addition, we confirmed the oncogenic role of TACC3 in bladder cancer through a series of functional tests." (PMID 29358577, 2018). "However, the potential role of TACC3 and its molecular mechanisms in bladder cancer remain to be addressed." (PMID 29358577, 2018).